RNU1-7P (RNA, U1 small nuclear 7, pseudogene)
Synonyms: RNU1-7
Gene: Small nuclear RNA gene on chromosome 1 (8,206,434 to 8,206,597, reverse strand). Ensembl gene ENSG00000200975.
Homologues: Orthologues: chimpanzee U1 (99% identical), macaque U1 (92% identical), rabbit U1 (65% identical). Paralogues in human: RNU1-1 (82% identical), RNU1-2 (82% identical), RNU1-27P (82% identical), RNU1-28P (82% identical), RNU1-3 (82% identical), RNU1-4 (82% identical), RNU1-67P (82% identical), RNVU1-18 (82% identical), RNVU1-29 (82% identical), U1 (82% identical), RNU1-89P (82% identical), RNVU1-28 (82% identical), and 133 more.